S1PR5 (sphingosine-1-phosphate receptor 5)
Diseases named in the same sentence as S1PR5 in open-access papers:
S1PR5 is named in the same sentence as 56 diseases in open-access papers, as found by Europe PMC text mining. Sharing a sentence is not in itself a finding about the gene and the disease. The quoted sentences say what the papers report.
multiple sclerosis (8 papers, 2012 to 2025). A progressive autoimmune disorder affecting the central nervous system resulting in demyelination. "In March 2020, ozanimod capsules, agonists for S1PR1 and S1PR5, were approved for application in the treatment of relapsing forms of multiple sclerosis by the US FDA, involving clinically isolated syndrome, relapsing-remitting disease, and active secondary progressive disease in adults." (PMID 34751249, 2021). "S1P modulators such as ceralifimod (selective S1PR1 and S1PR5 modulator), GSK2018682 (selective S1PR-1 and S1PR-5 modulator), and amiselimod (MT-1303) (selective S1PR-1 modulator) have been developed by different drugs companies to treat patients with multiple sclerosis." (PMID 35805142, 2022).
esophageal cancer (4 papers, 2021 to 2024). A primary or metastatic malignant neoplasm involving the esophagus. "Contrary to the pro-tumor roles of S1PR1, S1PR2, and S1PR3, S1PR5 was claimed to exert inhibitory effects on the proliferation and migration of esophageal cancer via the Ras/ERK, PI3K/Rac and Rho/ROCK signaling pathways." (PMID 34831211, 2021). "Although S1PR5 was originally believed to be primarily located in the nervous system, recent research has indicated that it is also involved in the proliferation and migration of gastric and esophageal cancer cell lines." (PMID 38312843, 2024). "Importantly, down-regulation of S1PR5 may be an important escape mechanism for esophageal cancer." (PMID 34831211, 2021).
prostate carcinoma (4 papers, 2020 to 2025). A carcinoma that arises from epithelial cells of the prostate gland. "Study in prostate cancer cells corroborated pro-survival role of S1PR5 by demonstrating that exogenous S1P-induced autophagy under serum-deprived conditions was associated with S1PR5 activation." (PMID 32456134, 2020). "In prostate cancer cells, extracellular S1P activates S1PR5, which triggers autophagy through endoplasmic reticulum stress." (PMID 40906080, 2025).
atherosclerosis (3 papers, 2022 to 2025). A disease characterized by the build-up of fatty material and calcium deposition in the arterial wall resulting in partial or complete occlusion of the arterial lumen. "Although these findings may suggest an indirect involvement of S1PR4 and S1PR5 in atherosclerosis-associated inflammation, the latter receptors seem to have less of a direct impact on atherosclerosis pathology." (PMID 36233252, 2022). "There are few studies on the mechanistic link between S1PR5 and atherosclerosis, but some studies have suggested that S1PR5 could be a potential noninvasive screening biomarker for coronary heart disease." (PMID 39920588, 2025).
Nephropathy (3 papers, 2022 to 2024). A nonspecific term referring to disease or damage of the kidneys. "Mice deficient in S1PR5 displayed reduced tissue damage and fibrosis, along with improved renal function in adenine-induced nephropathy." (PMID 39384640, 2024). "However, further research is needed to decipher the precise mechanisms and interactions of S1PR5 in renal disease." (PMID 39384640, 2024). "Among the predicted mRNAs, S1PR5, STAT3, TBR1, and BMPR1B were found to be related to some kidney diseases, as well." (PMID 36536378, 2022). "Moreover, among the predicted targeted mRNAs, S1PR5, STAT3, TBR1 and BMPR1B were found to be related to some kidney diseases." (PMID 36536378, 2022).
Cerebral ischemia (2 papers, 2018 to 2022). Restriction of arterial blood supply to the brain associated with insufficient oxygenation to support the metabolic requirements of the tissue. "However, it is not clear whether S1PR4 or S1PR5 are involved in the pathogenesis of cerebral ischemia." (PMID 35242008, 2022).
diabetes (2 papers, 2022 to 2024). "S1PR5 expression was correlated with diabetes, heart rate, triglycerides, total cholesterol, low-density lipoprotein cholesterol, apolipoprotein B, and fasting blood glucose (P < 0.05)." (PMID 35837598, 2022). "In the patient group, S1PR5 was correlated with diabetes, heart rate, triglycerides (TG), total cholesterol (TC), low-density lipoprotein cholesterol (LDL-C), apolipoprotein B (ApoB), and fasting blood glucose (P < 0.05); CARNS1 was correlated with uric acid (UA) (P < 0.05)." (PMID 35837598, 2022). "Spearman correlation analysis between their expression and clinical parameters showed that S1PR5 was associated with diabetes, heart rate, TG, TC, LDL-C, ApoB, and fasting blood glucose, while CARNS1 was associated with uric acid, suggesting S1PR5 and CARNS1 may be related to CHD." (PMID 35837598, 2022). "Diabetes, TG, TC, LDL-C, ApoB, and UA are CHD-related metabolism indicators, suggesting S1PR5 and CARNS1 may be related to the pathogenesis of CHD." (PMID 35837598, 2022). "After adjusting for age, body mass index, sex, hypertension, diabetes, smoking, TC, LDL-C, ApoA, and ApoB, S1PR5 was correlated with CHD (odds ratio 2.164, 95% CI: 1.670–2.804, P < 0.05), suggesting that higher S1PR5 expression may increase the risk of CHD." (PMID 35837598, 2022). "Therefore, we have not investigated diabetes-induced alterations of S1PR5 density in the present study." (PMID 37794263, 2024).
glioblastoma (2 papers, 2017 to 2025). The most malignant astrocytic tumor (WHO grade IV). "Interestingly, the expression of S1PR5 blocks the proliferation of this glioblastoma cell lines." (PMID 29149079, 2017).
lung carcinoma (2 papers, 2022 to 2023). "We found that lung cancer tissues expressed mainly S1PR1, S1PR2 and S1PR3, whereas S1PR4 and S1PR5 were undetectable, probably because they are highly restricted to distinct cell types and tissues, such as the lymphoid tissues, brain, and spleen." (PMID 37446018, 2023). "Indeed, we demonstrated that S1PR1, S1PR2, S1PR3, and S1PR5, but not S1PR4 are correlated with worse lung cancer patient prognosis." (PMID 35897763, 2022).
Anxiety (1 paper, 2021). Intense feelings of nervousness, tension, or panic often arise in response to interpersonal stresses. "Since both EAE+FTY720L and EAE+FTY720H combinations are anxiogenic, it can be concluded that there is an association between anxiety-like behavior and upregulation of S1PR5." (PMID 34177891, 2021). "Therefore anxiety-like behavior resulting from high dose FTY720 is associated principally with increased S1PR5 expression and to a lesser extent with decrease of S1PR1." (PMID 34177891, 2021).
chronic obstructive pulmonary disease (1 paper, 2020). A chronic and progressive lung disorder characterized by the loss of elasticity of the bronchial tree and the air sacs, destruction of the air sacs wall, thickening of the bronchial wall, and mucous accumulation in the bronchial tree. "In addition, a recent report revealed that macrophage function in chronic obstructive pulmonary disease was under epigenetic control of specific target genes by DNA methylation, and reduced methylation of the S1PR5 gene promoter may underlie impaired efferocytosis." (PMID 33597922, 2020).
Cognitive impairment (1 paper, 2026). Abnormal cognition is characterized by deficits in thinking, reasoning, or remembering. "DSS improved VaD cognitive impairment by modulating sphingolipid metabolism and promote myelin regeneration via activating the SPHK2/S1P/S1PR5 signaling pathway." (PMID 41495814, 2026).
depression (1 paper, 2019). "Moreover, GPCRs (including ADGRA1, ADGRV1, CELSR2, and S1PR5) previously reported to be implicated in the physiopathology and pharmacology of depression were also significantly altered." (PMID 30983951, 2019).
epilepsy (1 paper, 2021). A brain disorder characterized by episodes of abnormally increased neuronal discharge resulting in transient episodes of sensory or motor neurological dysfunction, or psychic dysfunction. "Integrating this evidence, we speculate that PRKCH and S1PR5 may induce resistance in patients with drug-treated epilepsy through the CREB pathway." (PMID 34805265, 2021).
hemorrhagic stroke (1 paper, 2023). A stroke caused by a bleed on the brain. "Siponimod, a new selective modulator of S1PR1 and S1PR5 with a short half-life and a better safety profile, has gained considerable attention as an immunomodulatory agent for the treatment of ischemic or hemorrhagic stroke in animals." (PMID 37191423, 2023).
injury (1 paper, 2025). Damage inflicted on the body as the direct or indirect result of an external force, with or without disruption of structural continuity. "Notably, we observed that SPHK1, S1PR3, and S1PR5 in the sphingolipid metabolism pathway could be potential therapeutic targets for the prevention of acute liver injury induced by APAP, as mediated by the Ks extract." (PMID 40811614, 2025).
ischemia reperfusion injury (1 paper, 2017). Adverse functional, metabolic, or structural changes in ischemic tissues resulting from the restoration of blood flow to the tissue (reperfusion), including swelling; hemorrhage; necrosis; and damage from free radicals. "Multiple studies demonstrated a protective effect in ischemia-reperfusion injury using fingolimod (agonist for S1PR1, S1PR3, S1PR4, and S1PR5) in different organs including the heart." (PMID 28596734, 2017).
Parkinson disease (1 paper, 2024). A progressive degenerative disorder of the central nervous system characterized by loss of dopamine producing neurons in the substantia nigra and the presence of Lewy bodies in the substantia nigra and locus coeruleus. "S1pr1 and S1pr5 are expressed by several cell types of the central nervous system, including microglia, which produce pro-inflammatory cytokines and molecules, and are closely related to Parkinson’s disease." (PMID 39451223, 2024).
psoriasis (1 paper, 2023). An autoimmune condition characterized by red, well-delineated plaques with silvery scales that are usually on the extensor surfaces and scalp. "Although it remains to be examined directly whether S1PR5 affects the pathogenesis of psoriasis, there are several reports of S1PR modulators also acting on S1PR5, influencing psoriasis." (PMID 37830566, 2023).
schizophrenia (1 paper, 2020). A major psychotic disorder characterized by abnormalities in the perception or expression of reality. "We found a negative correlation between S1PR5 expression level and the RIN in the corpus callosum, indicating that a lower RIN or associated phenomena may contribute to elevated S1PR5 expression in the corpus callosum of patients with schizophrenia." (PMID 32346731, 2020). "Expression of both S1PR1 and S1PR5 was also significantly higher in patients with schizophrenia than in controls (P = .02 and P = .03, respectively)." (PMID 32346731, 2020). "In the BA8, higher expression of S1PR1, but not S1PR5, was found in patients with schizophrenia than in controls." (PMID 32346731, 2020).
Sepsis (1 paper, 2023). Sepsis is defined as life-threatening organ dysfunction caused by a dysregulated host response to infection. "S1PR5, GNLY, CD247, KLRG1, IL-1R2, AUTS2, IL-2Rβ, ARG1, TGFBR3, TLR5 and PRF1 in the top 80 genes in the two modules were located toward the center of the co-expression network, and CD247, IL-2Rβ, TGF-βR3 and IL-1R2 were identified as core genes in sepsis." (PMID 36855106, 2023).
cancer (18 papers, 2014 to 2025). A tumor composed of atypical neoplastic, often pleomorphic cells that invade other tissues. "The S1P axis has been implicated in cancer and inflammatory diseases, and S1pr5 is a good candidate modulator of the differential inflammation and HCC susceptibility of AIRmax and AIRmin mice." (PMID 31049358, 2019). "For example, FTY720, an S1P modulator that binds to S1PR1, S1PR3, S1PR4, and S1PR5, has been shown to inhibit tumor growth and aggressiveness in various cancer models." (PMID 37744269, 2023). "Although there is limited data on the function of S1PR5 in tumor-infiltrated leukocytes and its contribution to tumor progression, some recent studies correlated the expression of S1PR5 on Trm or effector memory T cells (Tem) with cancer prognosis." (PMID 35163211, 2022). "There, clusters of HBV-specific Trm T cells were identified that showed reduced expression of S1PR5 and whose presence correlated with long-term relapse-free survival of cancer patients." (PMID 35163211, 2022). "For instance, FTY720, an S1P agonist that binds to S1PR1, S1PR3, S1PR4, and S1PR5, has been indicated to suppress the growth and aggressiveness of tumor in several cancer models." (PMID 31807117, 2019). "In relation to this, S1PR5 depletion could help in retaining NK cells within the BM, since the S1P concentration is elevated in the plasma of cancer patients and is higher compared to the concentration in BM of AML patients." (PMID 38182818, 2024). "S1PR4 is predominantly found in hematopoietic tissues and endothelial cells under basal conditions, whereas S1PR5 expression is restricted to NK cells, DCs, the central nervous system, endothelial cells, and certain cancer cells, indicating specialized functions of these two S1PRs." (PMID 35163211, 2022). "S1PR5 has been demonstrated to support cancer cell growth and survival." (PMID 32456134, 2020). "In addition, S1PR4 and S1PR5 play important roles in inflammation, which is also closely related to the progression of some cancers, such as colon cancer." (PMID 31807117, 2019). "Moreover, S100A4, S1PR5 and KLRG1, are biomarkers of therapeutic efficacy in mouse cancer models and patients with cancer." (PMID 40574416, 2025). "Therefore, several selected markers such as CX3CR1, A100A4, KLRG1, S1PR5, and S100A8 were investigated in cancer mouse models and patients with lung cancer to verify the feasibility of utilizing these markers to identify non‐responders and predict immunotherapy efficacy." (PMID 40574416, 2025). "The roles of S1PR4 and S1PR5 in cancer have not been completely elucidated." (PMID 32456134, 2020).
tumor (16 papers, 2013 to 2025). "Studies from other patient tumor samples have implicated S1PR5 as an independent prognostic factor in GBM, which aligns with data that S1PR5 increased proliferation." (PMID 32977496, 2020). "Furthermore, MHC class Ib-restricted CD8+ T cells that showed potent anti-tumor efficacy when injected into tumor-bearing mice exhibited high S1PR5 expression associated with rapid proliferation and prolonged persistence at the tumor site." (PMID 35163211, 2022). "Future studies will however be required to explore the role of these receptors in vivo to understand the intricacies of each function orchestrated by CXCR4 and S1PR5 in tumor-infiltrating NK cells." (PMID 40155684, 2025). "All these findings considered, we speculate that tumor cells benefit from NK cells expressing CXCR4 and S1PR5 in two ways: retaining NK cells in the tumor periphery and desensitizing NK cells to stimulation before they reach the tumor stroma." (PMID 40155684, 2025). "S1PR5, which regulates T-cell infiltration and emigration from peripheral organs, was shown to stimulate mitotic progression in HeLa cells, suggesting S1PR5 as a possible therapeutic target for inhibiting tumor proliferation." (PMID 35565311, 2022). "Irrespective of these remaining questions, the picture emerges that targeting individual sphingosine kinases or selected S1P receptors such as S1PR4 or S1PR5 may have the highest potential in unleashing the power of the anti-tumor immune response." (PMID 35163211, 2022). "Fingolimod, an agonist of four S1PRs (including S1PR1, S1PR3, S1PR4, and S1PR5), induces receptor internalization and exerts antagonistic effects, which could markedly reduce the tumor load and abrogate the NF-κB/IL-6/STAT3/S1PR1 cascade." (PMID 34831211, 2021). "Thus, S1PR5 harbors the potential to be an important marker of tumor-reactive T cells and its inhibition may promote anti-tumor immune memory." (PMID 35163211, 2022). "By contrast, treatment with BAF312 prevented the tumor-induced increase of NK cells and GrB+ NK cells in the BM but did not affect the frequency of BM Th1 cells, demonstrating that S1PR5 signaling mediates the egress of NK cells from the gut and their homing to the BM." (PMID 35503658, 2022). "Genes such as ADGRG1, TBX21, S1PR5, FCRL6, and FCGR3A showed relatively selective expression in tumor-reactive T cells (the average expression in bystander T cells < 0.5)." (PMID 39243082, 2024). "In line with our observations, SPHK1 expression relative to CXCR4 as well as CXCL12 relative to S1PR5 correlated positively in tumor biopsies but not in the respective normal control tissue." (PMID 40155684, 2025). "Although we cannot rule out a contribution from S1PR5, we conclude that the in vitro migration of monocytes and macrophages to tumor-derived S1P is S1PR1-dependent." (PMID 38339325, 2024). "In summary, whereas studies on the role of S1PR5 signaling on tumor-specific NK cells are lacking and may be a focus of future efforts, literature indicates that S1PR5 expression dictates the phenotype of tumor-infiltrating T cells with high expression on Tem and low on Trm T cells." (PMID 35163211, 2022). "S1PR5 knockdown did not affect clone formation by HCT116 cells, suggesting that S1PR5 does not affect tumor proliferation (P>0.05)." (PMID 38312843, 2024).
cardiovascular disease (1 paper, 2022). "No clinical studies have investigated the correlation between S1PR5 and cardiovascular disease." (PMID 35837598, 2022).
S1PR5 also shares sentences with these, for which no sentence is quoted: coronary heart disease (3 papers); ulcerative colitis (3); colon cancer (2); colorectal cancer (2); inflammatory bowel disease (2); melanoma (2); neurological disease (2); renal fibrosis (2); secondary progressive multiple sclerosis (2); systemic sclerosis (2); autoimmune disease (1); autoimmune peripheral neuropathy (1); cardiac hypertrophy (1); colitis (1); COVID-19 (1); diabetic retinopathy (1); esophageal squamous cell carcinoma (1); fibrosis (1); gastric cancer (1); hydronephrosis (1); Hypertension (1); immune diseases (1); infection (1); kidney injury (1); Myocardial fibrosis (1); neurodegenerative disease (1); oesophageal cancer (1); pneumonia (1); pterygium (1); relapsing remitting MS (1).
A further 2 diseases each share a sentence with S1PR5 in 1 paper.